NRP1 (neuropilin 1)
Diseases named in the same sentence as NRP1 in open-access papers (continued):
Sharing a sentence is not in itself a finding about the gene and the disease.
melanoma (continued). "In order to understand the molecular mechanisms involved in the melanoma invasive phenotype induced by PDGF-C, we have investigated the pattern of EMT-related protein expression in NRP-1-negative and -positive cells." (PMID 28977999, 2017). "Results indicated that PDGF-C directly interacts with NRP-1 in vitro and stimulates ECM invasion and vasculogenic mimicry in human melanoma cells expressing NRP-1 but lacking other VEGFRs and PDGFRs." (PMID 28977999, 2017). "Generally, NRP1 is predominantly found in carcinoma while NPR2 is expressed in non-epithelial tumors, such as melanoma, leukemia, neuroblastoma, and OS." (PMID 25890345, 2015). "In conclusion, evidences are presented demonstrating NRP-1 activation by PDGF-C and strongly suggesting that PDGF-C/NRP-1 signaling might be relevant in the metastatic switch of melanoma cells, even in the absence of PDGFRα." (PMID 28977999, 2017). "Although our data indicate that Gal-1 and NRP1/EGFR upregulation is a frequent adaptive mechanism in melanoma cells treated with BRAF inhibitors, this signaling cascade may not be critical in every case of melanoma developing drug resistance." (PMID 32784465, 2020).
gastric cancer (65 papers, 2003 to 2025). A primary or metastatic malignant neoplasm involving the stomach. "This publication aims to systematically assess the relationship between NRP-1 protein expression and the clinicopathological characteristics associated with gastric cancer by reviewing the existing literature on this topic." (PMID 40430075, 2025). "In this regard, only one meta-analysis has been conducted, including gastric cancer studies, in which the NRP1 association with different clinicopathological features was assessed, but prognosis parameters were not analyzed." (PMID 35884516, 2022). "Neurociliary protein-1 (NRP1) is highly expressed in progressive gastric cancer and is associated with a poor prognosis." (PMID 36313365, 2022). "The pooled results indicated that there was a significant association between NRP1 expression and the tumor stage of gastric cancer (early stage versus advanced stage: OR = 0.128, 95%CI = 0.059 − 0.277, P ≤ 0.001)." (PMID 33014187, 2020). "Further studies with larger samples and different ethnicities are required to confirm an association between NRP1 protein expression and the clinicopathological features of gastric cancer." (PMID 33014187, 2020). "There was no statistical significance association between the expression of NRP1 protein and gender, age, clinical stage, and Laurèn's classification in gastric cancer." (PMID 33014187, 2020). "The pooled results indicated that there was a significant association between NRP1 expression and the tumor size of gastric cancer (tumor size less than 5 cm versus more than 5 cm: OR = 0.443, 95%CI = 0.310 − 0.632, P ≤ 0.001)." (PMID 33014187, 2020). "In a xenograft mouse model of gastric cancer, NRP1-depletion causes upregulation of p27 and downregulation of cyclin E and Cyclin-dependent kinase-2 (CDK-2) and, thus, cell cycle arrest in the G1/S phase." (PMID 30717262, 2019). "Although NRP1 has been reported to be associated with poor prognosis and metastasis in gastric cancer patients, little is known about its role in regulating autophagy in gastric cancer." (PMID 37702613, 2023). "Additionally, NRP1 was found to be negatively associated with PFS in gastric cancer, NSCLC, and nasopharyngeal carcinoma, and disease-free survival (DFS) in osteosarcoma." (PMID 35884516, 2022). "This study aims to investigate whether NRP-1 expression is associated with the clinicopathology of gastric cancer, and involved in the growth and metastasis of gastric cancer cells." (PMID 26795388, 2016). "The authors observed that overexpression of Sema3A significantly attenuated the proliferation, migration, and invasiveness of gastric cancer cells, and this effect was associated with the inhibition of the PI3K/Akt pathway and reduced NRP-1 expression." (PMID 40430075, 2025). "Novel studies have shown also that NRP-1 expression in gastric cancer correlates with larger tumor size, advanced stages, lymph node metastasis, making it a potential therapeutic target." (PMID 40430075, 2025). "Further analysis demonstrated that RORA expression in gastric cancer is positively correlated with immune checkpoint-related genes, including NRP1 and CD40." (PMID 40638694, 2025). "Research into the therapeutic application of monoclonal antibodies targeting NRP-1 has yielded promising results in the context of gastric cancer treatment." (PMID 40430075, 2025). "Over the past decade, numerous studies have explored the expression of the neuropilin-1 (NRP-1) protein in gastric cancer, examining its correlation with various clinicopathological features." (PMID 40430075, 2025). "Specifically, NRP-1 has been shown to significantly influence the progression of gastric cancer by regulating tumor cell migration and invasion." (PMID 40430075, 2025). "For example, miR-206 has the ability to directly bind to the 3′UTR sequence of NRP-1, resulting in reduced expression of this co-receptor in gastric cancer cells and a reduction in their ability to proliferate and invade." (PMID 40430075, 2025).
gastric cancer (continued). "In many cancers, NRP1 serves as tumor promoter to participate in development of many cancers, including gastric cancer and lung cancer." (PMID 39014364, 2024). "In vitro experiments showed that NRP1 has the ability to regulate the proliferation and autophagy of gastric cancer cells by affecting the Wnt/β-catenin signalling pathway." (PMID 37702613, 2023). "In conclusion, we found that NRP1 can promote the proliferation of gastric cancer cells and inhibit the autophagy of gastric cancer cells." (PMID 37702613, 2023). "In vitro, we found that NRP1 promoted the proliferation but inhibited autophagy of gastric cancer cells, which was consistent with the previous report in colon cancer." (PMID 37702613, 2023). "Further elucidation of the interaction of NRP1 with autophagy and Wnt signaling pathways in gastric cancer is the focus of our next study." (PMID 37702613, 2023). "Migration and invasion of human gastric cancer cells can be suppressed by an anti-neuropilin-1 monoclonal antibody, anti-NRP1 mAb, through Akt dephosphorylation." (PMID 37894289, 2023). "After experiments, the results showed that NRP1 regulates the proliferation and autophagy of gastric cancer cells through the Wnt/β-catenin signaling pathway." (PMID 37702613, 2023). "We therefore propose that NRP1 can be used as both a prognostic factor and a therapeutic target through the regulation of autophagy in gastric cancer." (PMID 37702613, 2023). "Subsequently, we conducted a study on which signaling pathway NRP1 plays its role in gastric cancer." (PMID 37702613, 2023). "NRP1 interacts with fibrillin-1 (FN1) to promote the malignant progression of gastric cancer cells by affecting cell survival and migration through ECM remodeling." (PMID 36313365, 2022). "NRP1 has been identified as a key regulatory axis in gastric cancer, as evidenced by sequencing (Reference: GSE192631)." (PMID 35831348, 2022). "Similar findings, describing increased NRP1 levels in tumor tissue collected from gastric cancer, cervical cancer, NSCLC, bladder cancer, osteosarcoma, nasopharyngeal carcinoma, and renal cell carcinoma have been reported." (PMID 35884516, 2022). "For examples, oncogenic RBP Lin28 confers the stemness of gastric cancer by directly binding to coding protein NRP-1." (PMID 33589575, 2021). "MicroRNA-338 inhibits growth, invasion and metastasis of Gastric Cancer by Targeting NRP1 Expression57." (PMID 34702958, 2021). "Among the identified DEGs, we found that 7 genes (IGFBP7, LOX, NRP1, PRSS3, DPP3, EFNA3, and CD73) were also differentially expressed in tumor tissues and associated with a poor or better prognosis in patients with gastric cancer." (PMID 34659527, 2021). "EGF induces both expression of NRP-1 and VEGF, suggesting that the regulation of NRP-1 expression in gastric cancer is closely related to the EGF/EGFR system." (PMID 33167519, 2020). "The results indicated that well/moderate differentiation patients of gastric cancer had a much lower NRP1 expression rate versus poor differentiation group (OR = 0.735, 95%CI = 0.632 − 0.854, P ≤ 0.001)." (PMID 33014187, 2020). "Clinical case studies were included to compare the correlation between NRP1 protein expression and clinicopathological characteristics of gastric cancer." (PMID 33014187, 2020). "The study is aimed at evaluating the correlation between the expression of NRP1 protein and clinicopathological features of gastric cancer by meta-analysis." (PMID 33014187, 2020). "We confirmed higher expression of NRP1 mRNA in stomach cancer at multiple datasets using the various databases (Oncomine, GEPIA2, TIMER, and UALCAN)." (PMID 32408477, 2020). "In gastric cancer, NRP1 also acts as a receptor for major signaling pathways including vascular endothelial growth factor (VEGF), epidermal growth factor (EGF), and semaphorin-3A (SEMA3), showing an important role in tumor development and metastasis." (PMID 32408477, 2020).
gastric cancer (continued). "Knockdown of NRP1 expression by miR-338 inhibited gastric cancer cell migration, invasion, proliferation and promoted apoptosis." (PMID 32408477, 2020). "In particular, hypomethylated NRP1 gene has a positive correlation with poor prognosis in gastric cancer." (PMID 32408477, 2020). "In the Oncomine database, NRP1 mRNA expression demonstrated upregulation of NRP1 in lymphoma, brain and central nervous system (CNS), kidney, leukemia, sarcoma, and gastric cancer tissues compared to normal tissues (p-value: 1 × 10−4, fold-change: 2)." (PMID 32408477, 2020). "Depletion of NRP1 reduces cell proliferation via inhibiting the G1-S phase of cell cycle in gastric cancer cells." (PMID 32408477, 2020). "Studies indicated that NRP1 is abnormally expressed in a variety of tumor cells, including gastric cancer." (PMID 33014187, 2020). "Increased NRP1 mRNA and protein expression in stomach cancer tissue was already suggested in a previous report." (PMID 32408477, 2020). "This study also demonstrates that NRP1 expression correlates with immune cell infiltration in stomach cancer." (PMID 32408477, 2020). "NRP1 expression rate in patients with stages I and II gastric cancer was much lower than those with III and IV gastric cancer (OR = 0.736, 95%CI = 0.589 − 0.919, P = 0.007)." (PMID 33014187, 2020). "Although previous studies have investigated the roles of NRP1 in the progression of gastric cancer in vivo and in vitro, the clinical relevance of NRP1 in gastric cancer has not been fully understood." (PMID 32408477, 2020). "The expression of NRP1 protein in gastric cancer is closely correlated to clinical stage, tumor size, TNM stage, differentiation, and lymph node metastasis." (PMID 33014187, 2020). "For over a decade, a number of studies have examined the expression of NRP1 protein in gastric cancer and analyzed the relationship between the abnormal expression of NRP1 protein and the clinicopathological characteristics of gastric cancer." (PMID 33014187, 2020). "Serum sample 31# was from a gastric cancer patient, and the concentrations of Nrp1 and Nrp2 in the serum were 8630 and 8009 pg/mL, which were 12.9‐ and 17.4‐fold the mean values for serum from normal human samples." (PMID 30758083, 2019). "The transcription factor SOX10 induces among others the expression of miR338-p, which in gastric cancer and oral squamous carcinoma, inhibits the expression of NRP1 via phosphorylation of ERK1/2, MAPK, and AKT." (PMID 30717262, 2019). "Tumor cell NRP1 expression was more consistently detected; 50–80% of the samples for hepatocellular carcinoma, pancreatic adenocarcinoma, squamous cell carcinoma, and testis and stomach cancers showed expression of NRP1 transcripts in tumor cells." (PMID 30027561, 2018). "VEGR2/NRP1 trans‐complex formation was identified at low density in human gastric cancer (GAC) and at high density in PDAC." (PMID 30027561, 2018). "NRP-1 depletion inhibited the proliferation and migration of gastric cancer cells, and suppressed their ability to form tumors and to metastasize to lungs, and therapeutic NRP-1 shRNA inhibited the growth of established gastric tumors in experimental animals." (PMID 26795388, 2016). "In summary, NRP-1 is overexpressed in gastric cancer tissues, and its expression correlates with the clinical staging, tumor differentiation and pathological types of gastric cancer." (PMID 26795388, 2016). "Representatively, gastric adenocarcinoma expressed relatively lower levels, while undifferentiated gastric cancer, relatively higher levels of NRP-1." (PMID 26795388, 2016). "The expression of NRP-1 in a panel of human gastric cancer cells was examined by real-time RT-PCR and immunoblotting." (PMID 26795388, 2016). "Normal gastric mucosa had weak NRP-1 expression, whereas gastric cancer tissues expressed different levels of NRP-1 protein." (PMID 26795388, 2016).
gastric cancer (continued). "In accord, the present results have demonstrated that depletion of NRP-1 inhibited the proliferation of gastric cancer cells by inducing cell cycle arrest in the G1/S phase through upregulating p27 and downregulating cyclin E and CDK2." (PMID 26795388, 2016). "NRP-1 expression in clinical gastric cancer specimens was examined by immunohistochemistry and its association with clinicopathology analyzed." (PMID 26795388, 2016). "It has been reported that NRP-1 is expressed in human gastric cancer cells and in limited number of human gastric cancer tissues." (PMID 26795388, 2016). "NRP1 has been reported to be an important molecule that drives gastric cancer migration and invasion." (PMID 24736504, 2014). "In the present study, we found that in gastric cancer, overexpressed NRP1 promoted EMT and siNRP1 restrained EMT, whereas the forced expression of miR-338 inhibited EMT." (PMID 24736504, 2014). "RT–PCR revealed that five (TMK-1, AGS, NCI-N87, ST-2, ST-7) of seven gastric cancer cell lines constitutively expressed NRP-1 mRNA." (PMID 12618892, 2003). "In our study, NRP-1 mRNA expression was induced by EGF treatment at 24 h in three different gastric cancer cell lines (AGS, NCI-N87, and ST-2)." (PMID 12618892, 2003). "According to recent reports, Sema3A may play an antitumor role in gastric cancer by acting as an inhibitor of NRP-1 activity." (PMID 40430075, 2025). "Although the direct link between circNRIP1 and NRP-1 has not been clearly confirmed, there is evidence that other circRNAs, such as circHIPK3, can regulate NRP-1 expression through interactions with miR-653-5p and miR-338-3p, thereby affecting the migration and invasion of gastric cancer cells." (PMID 40430075, 2025). "Additionally, studies have shown that NRP-1 functions as a co-receptor for c-Met in other malignancies, such as gastric cancer and cholangiocarcinoma, where it facilitates tumor progression." (PMID 40419692, 2025). "Furthermore, in a mouse model of human gastric cancer xenografts, administration of anti-NRP-1 mAb resulted in a marked reduction in both tumor volume and weight, without exhibiting any discernible toxic effects." (PMID 40430075, 2025). "NRP1 depletion inhibits gastric cancer cell proliferation by inducing cell cycle arrest and upregulating p27 while downregulating cyclin E and cyclin-dependent kinase 2 in addition to suppressing cell migration by inhibiting focal adhesion kinase phosphorylation." (PMID 37894289, 2023). "However, it has also acted as a tumor suppressor by inhibiting tumorigenesis and chemosensitivity by targeting neuropilin-1 in gastric cancer cases." (PMID 37925170, 2023). "In this way, LIN28B promotes transformation and migration in colon cancer through LGR5, PROM1, and CDX2 mRNAs, promotes stemness and EMT in gastric cancer through NRP-1 mRNA, inhibits apoptosis in ovarian cancer through AKT2 mRNA, and promotes migration in neuroblastoma through MYCN-induced mRNAs." (PMID 37370851, 2023). "In a study performed with osteosarcoma patients, elevated levels of NRP1 forecasted lower chemotherapeutic response, and higher NRP1 plasma levels were established as predictors of bevacizumab efficacy in patients with gastric cancer." (PMID 35884516, 2022). "Moreover, circHIPK3 facilitated gastric cancer metastasis through interacting with miR-653 and miR-338-3p to modulate NRP1 expression under hypoxia." (PMID 35379058, 2022). "For instance, miR-9-5p could suppress tumor proliferation and migration in gastric cancer by targeting neuropilin-1, but it acted as an oncogene promoting angiogenesis and invasion by inhibiting SOCS5 in cervical cancer." (PMID 35179718, 2022). "This study determined that NRP1 was a gene that promotes gastric cancer." (PMID 33995640, 2021). "NRP1 plays an essential role in the proliferation, migration, and invasion of gastric cancer cells." (PMID 33976744, 2021). "As reported in gastric cancer, miR-19b-3p was downregulated and negatively regulated neuropilin-1." (PMID 34282711, 2021).